CSF1 (colony stimulating factor 1)
Diseases named in the same sentence as CSF1 in open-access papers (continued):
Sharing a sentence is not in itself a finding about the gene and the disease.
Crohn disease (4 papers, 2017 to 2019). A gastrointestinal disorder characterized by chronic inflammation involving all layers of the intestinal wall, noncaseating granulomas affecting the intestinal wall and regional lymph nodes, and transmural fibrosis. "A recent example is a frame-shift mutation in the CSFR2B gene, also highly-expressed in monocytes and regulated by CSF1 and LPS, associated with Crohn’s disease in Ashkenazi Jews." (PMID 28263993, 2017). "Both IL34 and CSF1 transcripts were elevated in inflamed gut tissues from Crohn's disease (CD) or ulcerative colitis (UC) patients compared to non-IBD control diverticulitis and normal tissues that were tumor-adjacent." (PMID 31552020, 2019). "Collectively, the data supported a hypothesis that CSF-1 driven biology is elevated in Crohn’s disease mucosa, even more so in infliximab non-responders." (PMID 31710624, 2019).
cyst (4 papers, 1998 to 2024). A sac-like closed membranous structure that may be empty or contain fluid or amorphous material. "The concentration of each antigen was significantly higher in patients with malignant tumour than with benign neoplasm in each comparison, except for ICTP in peritoneal fluid and for CSF-1 in cyst fluid." (PMID 9667653, 1998). "The chemokine profile is different compared to trophozoites, the main up-regulated chemokines are the same, but CCL4, CCL4L2, CSF1, CCL5, CXCL5, and CX3CL1 are more highly up-regulated in the cyst interaction." (PMID 35573800, 2022).
diffuse-type giant cell tumors (4 papers, 2017 to 2025). "The specificity of these agents and their potent blocking activity has been substantiated by impressive response rates in diffuse-type tenosynovial giant cell tumors, a benign connective tissue disorder driven by CSF1 in an autocrine fashion." (PMID 28716061, 2017). "However, depleting TAMs with CSF1/CSF1R blockers has limited monotherapy efficacy, except in diffuse-type giant cell tumours that overexpress CSF1, because the benefits from TAM depletion are counteracted by enhanced recruitment of granulocytic myeloid-derived suppressor cells (MDSCs)." (PMID 38831013, 2024). "Studies of TAM depletion strategies with limited efficacy in most cancers, including CSF1/CSF1R inhibitors (e.g., PLX3397), showed limited monotherapy efficacy, except in CSF1R-driven tumors, like diffuse-type giant cell tumors." (PMID 40422244, 2025).
esophageal squamous cell carcinoma (4 papers, 2023 to 2025). Esophageal squamous cell carcinoma (ESCC) is a type of esophageal carcinoma (EC) that can affect any part of the esophagus, but is usually located in the upper or middle third.
ischemic stroke (4 papers, 2019 to 2023). A stroke disorder caused by obstruction of blood flow to the brain, due to thrombotic (local blood clot formation) or embolic (due to a blood clot or other material traveling from another site) event. "Recently, genetically predicted higher CSF-1 was shown to associate with higher risk of ischemic stroke in a Mendelian randomization study, indicating a plausible causal role." (PMID 37794467, 2023). "Using qPCR, we successfully validated several key genes regarding CD11c-associated molecules (Itgax, Gpnmb, Gpx3, Csf1, Spp1, Igf1) in the sham group, Day 7, Day 14, and Day 30 after ischemic stroke." (PMID 36828819, 2023). "Furthermore, we have detected Angiopoietin-like 4, which supported neurogenesis in an ischemic stroke rodent model, Decorin, which supported axon growth in the SCI model, as well as CSF1." (PMID 38025267, 2023).
liver cancer (4 papers, 2016 to 2024). An epithelial or non-epithelial malignant neoplasm that arises from the liver. "To further investigate the mRNA expression levels of SPP1 and CSF1 in different liver cancer samples from the TCGA database, we performed a subgroup analysis using the UALCAN database." (PMID 37097499, 2023). "We hypothesized that the expression levels of SPP1 and CSF1 were related to the prognosis of liver cancer patients." (PMID 37097499, 2023). "In addition, high CSF1 expression was also associated with poor OS in liver cancer patients who were male, did not consume alcohol, had HBV, and were Asian." (PMID 37097499, 2023). "In our study, the expression trend of SPP1 and CSF1 in HCC was consistent, which was verified using liver cancer cells in vitro." (PMID 37097499, 2023). "In liver cancer, HCC-derived CSF1 transforms macrophages to the M2 phenotype to drive immune escape and anti-PD1 tolerance." (PMID 37097499, 2023). "OPN was recently reported to be able to block the Th1-mediated immune response pathway by activating the colony-stimulating factor-1 (CSF1)/CSF1 receptor (CSF1R) pathway, leading to an increase in immunosuppressive cytokines in liver cancer." (PMID 37097499, 2023).
lung disease (4 papers, 2018 to 2021). "We used a transgenic murine model to demonstrate a pro-fibrotic role for CSF1 and AKT in the lungs, and believe that these observations may be applicable to clinical lung disease, as we showed overexpressing AKT predisposes lungs to fibrosis in the presence of bleomycin." (PMID 31750010, 2019). "In contrast to DFO, extracellular GSH did reduce a subset of pro-inflammatory factors by more than 10-fold, including the pro-inflammatory cytokines CCL20, CSF-1, and MCP-1 that in BALF from CF infants are correlated with oxidative stress and lung disease." (PMID 33613309, 2021).
malaria (4 papers, 2012 to 2021). Malaria is a serious and sometimes fatal disease caused by a parasite that commonly infects a certain type of mosquito which feeds on humans. "CD4+ T cells have been shown to produce IFN-γ and macrophage colony-stimulating factor (M-CSF or CSF1) that are important for the activation and expansion of CD169+ macrophages to control malaria blood-stage infection." (PMID 33344264, 2020). "Out of the six proteins, three were identified as showing increased levels (CRP, CSF1, LBP) in malaria patients compared to controls while the remaining three displayed decreased levels (CCL5, CTSD, SPARC)." (PMID 30442134, 2018).
neurofibroma (4 papers, 2017 to 2024). An intraneural or extraneural neoplasm arising from nerve tissues and neural sheaths. "We verified that neurofibroma SC conditioned medium contains macrophage chemo-attractants including colony stimulation factor 1 (CSF1)." (PMID 28256556, 2017). "We were able to verify that CSF1 protein is present in neurofibroma lysates, is present in neurofibroma SC medium, and can recruit macrophages." (PMID 28256556, 2017). "Autocrine (SC) and paracrine (SC → macrophage) Csf1-Csf1r interactions suggest a role for 7-month-old neurofibroma SCs in recruiting/polarizing macrophages within tumor microenvironment." (PMID 28256556, 2017). "Finally, we find that neurofibroma SCs secrete macrophage chemoattractants including CSF1 and that neurofibromas contain increased levels of numerous additional chemokines, cytokines, and growth factors, including IFN-γ." (PMID 28256556, 2017). "Thus, neurofibroma SCs secrete cytokines, including CSF1 that facilitate macrophage migration." (PMID 28256556, 2017). "Our gene expression data suggested the possibility that prolonged reduction of IFN-α/β in neurofibroma leads to the expression of IFN-γ and its target genes Csf1, Lif, Irf1, and Casp1 in SCs, possibly contributing to the recruitment and maturation of macrophages." (PMID 28256556, 2017). "Since CSF1 is a known macrophage chemoattractant and an interaction between CSF1 and is receptor CSF1R (FMS/CD115) was identified in our microarray data analysis, we tested if an anti-CSF1 function-blocking antibody might reduce macrophage migration stimulated by neurofibroma SC conditioned medium." (PMID 28256556, 2017).
parasitemia (4 papers, 2015 to 2018). "Consistent with the effects of MCSF blockade, Csf1ΔUbc mice exhibited significantly higher recrudescent parasitemia and lost more weight than control Csf1fl/fl mice." (PMID 27923070, 2016). "It is not yet clear whether or how the more modest effects of CD4+ T cell-specific Csf1 deletion on monocyte numbers and macrophage/monocyte activation contribute to the observed increases in parasitemia and morbidity in Csf1ΔCD4 mice." (PMID 27923070, 2016). "Colony-stimulating factor 1 (CSF-1) was proposed as a protein necessary to regulate the number of tissue-resident macrophages; nevertheless, it has been shown that interleukin-4 (IL-4) plays a major role in favoring the local proliferation of macrophages in parasitic infections." (PMID 26074923, 2015). "We measure the inducible upregulation of Csf1 in antigen-experienced CD4+ T cells from infected mice, and show that CD4+ T cell-derived MCSF is important for control of parasitemia and recovery of host health late in infection, coinciding with the kinetics of maximal myeloid expansion." (PMID 27923070, 2016).
preeclampsia (4 papers, 2021 to 2024). Preeclampsia is a hypertensive disorder of pregnancy that is characterized by new-onset hypertension with proteinuria presenting after 20 weeks of gestation, and depending on mild or severe forms may initially present with severe headache, visual disturbances, and hyperreflexia. "The CSF1 protein is pivotal in regulating placental trophoblast cell proliferation and development, contributing to conditions such as preeclampsia." (PMID 39273344, 2024). "CSF1 signaling via CSF1R promotes the growth, proliferation and migration of trophoblasts in humans and mice, and high CSF1 levels are correlated with preeclampsia development." (PMID 37012406, 2023).
renal carcinoma (4 papers, 2009 to 2022). A carcinoma arising from the epithelium of the renal parenchyma or the renal pelvis. "In human renal cancer, TEX express Csf-1, thereby promoting TAMs." (PMID 35393950, 2022).
acute kidney injury (3 papers, 2019 to 2023). Sudden and sustained deterioration of the kidney function characterized by decreased glomerular filtration rate, increased serum creatinine or oliguria. "Notably, CSF-1 can induce tubule proliferation, which is critical for kidney repair from acute kidney injury." (PMID 36978098, 2023).
acute liver failure (3 papers, 2016 to 2018). Rapid deterioration of liver function causing encephalopathy and coagulopathy. "In the context of models of acute liver failure, CSF1-Fc treatment rapidly expanded the Kupffer cell population and restored the capacity for removal of potential infections arriving in the portal blood." (PMID 29351395, 2018). "Although models of acute liver failure in pigs have been described, and may be one path to clinical development of CSF1-Fc as a treatment, it is challenging to perform sufficient replicates to test a clinical intervention." (PMID 27445344, 2016). "The fact that administration of CSF1-Fc to pigs increased the size of the liver and the liver macrophage population (i.e., the clearance capacity, noting also the increased expression of clearance receptors in the array profiles) has an obvious relevance to human acute liver failure." (PMID 27445344, 2016).
Autoimmunity (3 papers, 2012 to 2025). The occurrence of an immune reaction against the organism's own cells or tissues. "Following the aim to define specific molecules that drive both immunopathology and/or autoimmunity in inflammatory heart disease, here we report on increased expression of colony stimulating factor 1 (CSF-1) in patients with myocarditis." (PMID 30349538, 2018). "Since viral heart disease triggers heart-directed autoimmunity, in a second approach we investigated the influence of CSF-1 upon manifestation of heart tissue inflammation during experimental autoimmune myocarditis (EAM)." (PMID 30349538, 2018). "Therefore, we investigated the pathophysiological role of CSF-1 also in EAM, and started siCSF-1 treatment upon manifestation of myosin-heavy chain-directed autoimmunity 14 days after the first immunization." (PMID 30349538, 2018).
biliary tract cancer (3 papers, 2023 to 2025). "Recently, CSF1 was described as a potential preoperative plasma marker for biliary tract cancer." (PMID 40470116, 2025).
clear cell renal cell carcinoma (3 papers, 2015 to 2019). "This study aims to evaluate the impact of colony stimulating factor-1 (CSF-1) expression on recurrence and survival of patients with clear-cell renal cell carcinoma (ccRCC) following surgery." (PMID 25886010, 2015).
demyelinating disorders (3 papers, 2013 to 2024). "Specifically, our study links aberrant CSF-1 signaling to region-specific loss of a homeostatic phenotype (M0) and acquisition of a phenotype (MGnD) characteristic of degenerative and demyelinating disorders." (PMID 32430064, 2020). "Multiple studies have verified the role of the CSF-1/CSF-1R axis in the development of inflammatory and demyelinating disorders that affect the CNS." (PMID 38737586, 2024). "Although there is a paucity of direct research on CSF-1 in individuals with NMOSD, a multitude of similar immunological pathways exist in demyelinating disorders." (PMID 38737586, 2024).
esophageal cancer (3 papers, 2023 to 2024). A primary or metastatic malignant neoplasm involving the esophagus. "Esophageal cancer cells promote macrophage M2 polarization and recruitment through up-regulation of CSF1 and CCL20, respectively." (PMID 38600588, 2024). "For instance, FOXO1 promotes macrophage recruitment and M2-like macrophage polarization by enhancing the secretion of CSF-1 (colony-stimulating factor 1) and CCL20 (chemokine ligand 20) in esophageal cancer." (PMID 38714539, 2024).
fibrosis (3 papers, 2016 to 2024). the formation of excess fibrous connective tissue in an organ or tissue in a reparative or reactive process. "Here, we investigated the impact of CSF1-Fc on resolution of advanced fibrosis and liver regeneration, using a non-resolving toxin-induced model of chronic liver injury and fibrosis in C57BL/6J mice." (PMID 35169835, 2022). "To determine whether a less frequent CSF1-Fc treatment regime would effectively remodel the fibrotic scar, we investigated the impact of once weekly treatment on fibrosis regression." (PMID 35169835, 2022).
Hepatosplenomegaly (3 papers, 2014 to 2018). Simultaneous enlargement of the liver and spleen. "Treatment of adult mice with CSF1-Fc caused hepatosplenomegaly, associated with the proliferation of hepatocytes in the liver." (PMID 29351395, 2018). "Themost obvious effect of the CSF1-Fc was hepatosplenomegaly, which was visiblyevident upon necropsy, and which accounted for almost all of the body weightgain." (PMID 24962162, 2014). "The most obvious effect of CSF1-Fc administration was hepatosplenomegaly." (PMID 27445344, 2016).
Infertility (3 papers, 2017 to 2023). "Here, there was a 4.55-fold increase in CSF-1 expression for the infertile women who achieved pregnancy, suggesting that CSF-1 expression could improve IVF outcomes." (PMID 28830391, 2017).
kidney stone (3 papers, 2021 to 2023). "Our data suggest the important role of AR, miRNA and CSF-1 signaling in human nephrolithiasis pathogenesis." (PMID 37093310, 2023). "M2-macrophages associated phagocytosis could suppress kidney stone development through serval mechanisms, including NLRP3, miR-93-TLR4/IRF1, and miR-185-5p/CSF1 pathways." (PMID 36932340, 2023).
Listeria monocytogenes infection (3 papers, 2019 to 2020). "In a Listeria monocytogenes infection model, CSF-1/IL-34 blockade or treatment with anti-CSF-1 alone increased susceptibility to bacterial infection, although to a lower degree than anti-TNF therapy." (PMID 33162994, 2020). "Furthermore, evaluation of IL34 and CSF1 blockade treatment during Listeria infection reveals no substantial safety concerns." (PMID 31552020, 2019).
malignant glioma (3 papers, 2020 to 2026). A grade III or grade IV glioma arising from the central nervous system. "Thus, CSF‐1 is targeted directly by miR‐1254, and the miR‐1254/CSF‐1 axis may be a potential diagnostic target for malignant glioma." (PMID 31994318, 2020).
mantle cell lymphoma (3 papers, 2020 to 2021). Mantle cell lymphoma is a rare form of malignant non-Hodgkin lymphoma affecting B lymphocytes in the lymph nodes in a region called the ``mantle zone''. "In mantle cell lymphoma (MCL), the secretion of CSF-1 polarizes monocytes into specific CD163+ M2-like TAMs (MφMCLs), which promotes the proliferation of lymphoma cells." (PMID 34404434, 2021). "CSF-1 can be produced and secreted by adhering phagocytes but also by mantle cell lymphoma (MCL) cells." (PMID 32899476, 2020). "In mantle cell lymphoma (MCL), primary MCL cells transform monocytes into specific CD163+ M2-like macrophages by secreting CSF1 and IL-10." (PMID 32801364, 2020).
meningioma (3 papers, 2021 to 2024). A generally slow growing tumor attached to the dura mater. "In their study, the authors reported that treatment of murine meningiomas using anti-CSF1/CSF1R monoclonal antibodies, in contrast to anti-PD1 therapy, was efficacious and inhibited tumor growth." (PMID 39273576, 2024). "In 2021, Yeung and colleagues were the first to examine a macrophage-targeting approach in an immune-competent syngeneic mouse model of meningioma using anti-CSF1/CSF1R immunotherapy, which has been shown to induce anti-tumoral responses in other brain malignancies, such as glioma." (PMID 39273576, 2024).
myocardial infarction (3 papers, 2018 to 2024). Gross necrosis of the myocardium, as a result of interruption of the blood supply to the area, as in coronary thrombosis. "Five proteins deregulated in homozygous LAV-BPIFB4 carriers (e.g. CXCL11, CSF-1, SLAMF7, IL-10RB and TNFRSF9) emerged from a recent proteome-based CV risk model as the top factors predicting myocardial infarction event." (PMID 38468336, 2024). "After myocardial infarction an upregulation of CSF-1 is observed in ischemic areas for more than 5 days after the injury." (PMID 30349538, 2018).